VCAN (versican)
Diseases named in the same sentence as VCAN in open-access papers (continued):
Sharing a sentence is not in itself a finding about the gene and the disease.
breast carcinoma (continued). "Recently, various histotypes of breast in situ carcinomas have been examined in order to assess the immunohistochemical expression of versican in the stroma and correlate these findings to disease progression." (PMID 25140302, 2014). "On the other hand, the expression of versican in the cases of classic lobular in situ carcinomas was confined to the anatomical structures that usually contain this PG in adult breast tissues." (PMID 25140302, 2014). "Versican seems to have a prominent role in breast cancer progression due to its ability to interact with molecules determined to be regulators of key cellular processes." (PMID 25140302, 2014). "Structure-function studies focusing on versican suggest that its G3 domain is closely correlated to breast cancer progression." (PMID 25140302, 2014). "Analysis of clinical specimens showed elevated versican expression within the metastatic lung of patients with breast cancer." (PMID 25140302, 2014). "The purpose of this study was to determine the effects of the versican G3 domain on breast cancer cell invasion and migration to primary bone stromal and pre-osteoblast MC3T3-E1 cells." (PMID 22862967, 2012). "In the four mouse breast cancer cell lines 67NR, 66c14, 4T07, and 4T1, 4T1 cells expressed higher levels of versican, and showed higher migration and invasion ability to MC3T3-E1 cells and primary bone stromal cells." (PMID 22862967, 2012). "Previous studies shows that the activity of the versican G3 domain is important in breast cancer cell growth, migration and metastasis." (PMID 22862967, 2012). "In the field of cancer research several authors have previously identified high levels of tissue versican expression as an indicator for poor outcome in malignant diseases such as prostate cancer and breast cancer." (PMID 23024773, 2012). "Versican G3 domain enhanced breast cancer progression, metastasis, chemical reagent (i.e. chemotherapy) resistance, and tumor cell self-renewal is modulated by the up-regulation of Epidermal Growth Factor Receptor (EGFR)-mediated signaling." (PMID 22862967, 2012). "Researchers have previously analysed versican expression in areas adjacent to in situ and invasive carcinomatous areas in human breast cancer." (PMID 23082892, 2012). "Considering that CBMTs can serve as research models for tumour progression, the analysis of versican expression in these tumours can contribute to the understanding of the transformation and progression mechanisms in malignant mammary tumours." (PMID 23082892, 2012). "In our previous work we characterized the expression of versican in murine mammary epithelial tumor cell lines 67NR, 66c14, 4T07, and 4T1 (which were derived from a single spontaneous arising mammary tumor from Balb/cfC3H mice)." (PMID 22862967, 2012). "Researchers have demonstrated that in canine mammary tumours, versican is highly expressed in proliferating fusiform cells and in myxoid areas of the mixed tumours." (PMID 23082892, 2012). "A greater viability in low serum and serum-free conditions in the presence of versican G3 was observed in human breast cancer cells." (PMID 22096483, 2011). "An interesting observation of our study is the apparent dual roles of versican G3 domain in modulating breast cancer cell resistance to chemotherapy and EGFR targeting therapy." (PMID 22096483, 2011). "In order to investigate the effects of versican G3 domain on breast cancer cell apoptosis induced by chemotherapeutic drugs, we chose 5 frequently used compounds." (PMID 22096483, 2011). "In this study we also noted that versican G3 expressing breast cancer cells showed enhanced apoptosis when treated with certain chemicals, such as C2-ceramide and Docetaxel." (PMID 22096483, 2011). "To investigate the effects of versican G3 domain on breast cancer cell apoptosis, we exogenously expressed versican G3 in mouse mammary tumor cell lines 66c14, 4T07, 4T1, and human breast cancer cell lines MT1, MDA-MB-231, MCF-7, MDA-MB-468." (PMID 22096483, 2011).
breast carcinoma (continued). "In the majority of patients with breast cancer, increased staining for versican and decorin was found, in the peritumoral and intratumoral stroma." (PMID 21791066, 2011). "This supports further the notion of a positive role for versican in tumor growth and progression in breast cancer." (PMID 21791066, 2011). "EGFR signaling appears crucial to the sensitivity or resistance of versican expressing breast cancer cells to chemotherapy." (PMID 22096483, 2011). "In the current study, we demonstrated that versican G3-expressing breast cancer cells express enhanced cell survival in serum free medium and in response to certain chemotherapeutic drugs such as Doxorubicin and Epirubicin." (PMID 22096483, 2011). "In the present study, we have focused on the role of versican G3 domain in modulating breast cancer cell apoptosis." (PMID 22096483, 2011). "The expression of versican G3 domain does not only appear to enhance breast cancer cell proliferation in vitro and in the mammary gland, but also promotes tumor cell migration in vitro and systemic metastasis in syngenetic orthotopic models in vivo." (PMID 22096483, 2011). "Increased activation of EGFR and dysregulated expression of versican contributes towards a more aggressive human breast cancer phenotype." (PMID 22096483, 2011). "Extracellular versican has been observed to be elevated in a variety of human tumors including breast carcinoma." (PMID 22096483, 2011). "Higher expression of versican in 4T1 cell line than other three mouse breast cancer cell lines supports above explanation." (PMID 22096483, 2011). "The presence of two EGF-like domains in versican G3 and the importance of versican as a prognostic factor in breast cancer motivates further research in delineating the role of EGF receptors and the downstream signaling pathways in invasive breast cancer." (PMID 22096483, 2011). "It has been reported that versican and its G3 domain possess properties that promote cell growth and survival in low serum and serum-free conditions in breast cancer cells." (PMID 22096483, 2011). "Our experiments demonstrate that the sensitivity of breast cancer cells to chemotherapeutically induced apoptosis was versican G3 domain dependant." (PMID 22096483, 2011). "Versican G3 domain enhanced mouse breast cancer cell line 66c14, 4T07 and human breast cancer cell line MT1 and MDA-MB-468 survival in serum free medium." (PMID 22096483, 2011). "Both selective EGFR inhibitor AG 1478 and selective MEK inhibitor PD 98059 were observed to be able to block this signaling pathway and prevent versican G3 induced effects on mammary cancer cell proliferation." (PMID 22096483, 2011). "We have demonstrated that versican G3 domain appreciably increased breast cancer cell attachment, proliferation, and migration in vitro, and promoted local tumor growth and metastasis in vivo." (PMID 21079779, 2010). "We found that expression of versican 3′UTR in a mouse breast carcinoma cell line, 4T1, decreased miR-199a-3p levels." (PMID 21049042, 2010). "Versican G3 domain appears to be important in local and systemic invasiveness of human breast cancer." (PMID 21079779, 2010). "Versican G3 domain appreciably increased breast cancer cell attachment, proliferation, and migration in vitro." (PMID 21079779, 2010). "The presence of two EGF-like domains in versican G3 and the importance of versican as a prognostic factor in breast cancer add to the interest in further delineating the role of EGFR and downstream signaling in invasive breast cancer." (PMID 21079779, 2010). "To summarize, we have found that expression of versican G3 promoted breast cancer cell growth and metastasis through up-regulating active EGFR expression and activation of the EGFR-mediated pathway." (PMID 21079779, 2010). "To investigate the effect of versican G3 on breast cancer cell growth and metastasis, and its potential signaling pathways, we exogenously expressed a versican G3 construct in 66c14 cells." (PMID 21079779, 2010).
breast carcinoma (continued). "Here we evaluated the expression of versican in mouse mammary tumor cell lines observing that 4T1 cells expressed highest levels while 66c14 cells expressed low levels." (PMID 21079779, 2010). "In the current study, we have investigated the mechanisms of versican G3 domain effects on mouse mammary tumor cell growth, migration, and proliferation." (PMID 21079779, 2010). "Given the knowledge of systemic metastasis in breast cancer to preferentially seed certain anatomic sites notably bone, the relationship of breast cancer and versican in bone is of interest." (PMID 17662123, 2007). "Athymic rats injected with versican G3 transfected human breast carcinoma cells (MT-1) were observed to demonstrate a greater systemic tumor burden than animals injected with control cells." (PMID 17662123, 2007). "Extracellular PG-M/versican has been observed to be elevated in a variety of human tumors including breast carcinoma." (PMID 17662123, 2007). "Versican G3 also influences systemic metastasis in a murine model of metastatic human breast carcinoma." (PMID 17662123, 2007). "Versican G3 domain appears to be important in local and systemic tumor invasiveness of human breast cancer." (PMID 17662123, 2007). "Versican expression has been shown to be a predictor of breast cancer survival in women and increased versican expression in the peri-tumoral matrix is correlated with a higher risk of cancer relapse." (PMID 17662123, 2007). "Interestingly, MDH2 overexpression upregulated several genes associated with breast cancer metastasis (IL13RA2, MMP3, PTGS1, SYK, VCAN, and FLT1) and downregulated several genes associated with metastasis suppression (NOTCH3 and HTRA3)." (PMID 41179294, 2025). "Additionally, the TCGA dataset was used to correlate expression levels of CD8A (a marker indicative of CD8+ T cells) and VCAN across subtypes of breast cancer." (PMID 40361362, 2025). "VCAN accumulation within the stroma was abundant (score = 2–3) in 81.3% of breast cancers." (PMID 40361362, 2025). "Therefore, our study provided significant insights into the expression patterns of TGFβ1 and CXCR4 and their involvement with other proteins, for instance VCAN, and WNT whose role is known in causing breast cancer stemness and hence cancer aggressiveness." (PMID 41348904, 2025). "In this study, we aim to investigate the potential for the accumulation and proteolysis of versican to act as a biomarker for immunotherapy response in breast cancer by evaluating the relationship between versican, its proteolysis, and the infiltration of CD8+ tumor-infiltrating lymphocytes." (PMID 40361362, 2025). "Previously, RICCIARDELLI and collaborators, when analyzing VCAN in breast carcinomas of women, noticed that its expression was more evident and diffused around malignant areas, while the stroma surrounding areas considered benign showed negligible immunoreactivity for PG." (PMID 39682243, 2024). "Furthermore, VCAN released from bone marrow cells facilitates the metastasis of breast cancer, while VCAN expressed by CD11b + Ly6C-high cells induces lung metastasis through an EMT-dependent mechanism." (PMID 38791985, 2024). "Additionally, in vitro and in vivo studies of breast cancer have also shown that VCAN interacts with the microenvironment’s matrix, fibronectin and VEGF to promote angiogenesis." (PMID 37108649, 2023). "LncRNA versican (VCAN)-AS1 promotes breast cancer cell migration, invasion, and EMT by working as a competing endogenous RNA to inhibit miR-106a-5p, which cancer cell progression via targeting signal transducer and activator of transcription 3 (STAT3) and inhibiting the STAT3/HIF1α axis." (PMID 37583933, 2023). "The expression of VCAN and Snail in breast cancer tissue is significantly positively correlated." (PMID 37461061, 2023). "In addition, VCAN is a promising biomarker for the prognostic prediction of gastric cancer patients, breast cancer patients, and colorectal cancer patients." (PMID 36407083, 2022).
breast carcinoma (continued). "Of note, DACH1 and VCAN showed obvious upregulation in breast cancer with lymph node metastasis." (PMID 35211507, 2021). "Additionally, breast cancer-derived versican G3-domain suppresses the survival and differentiation of osteoblasts, suggesting a further contribution to osteolytic breast cancer bone metastasis." (PMID 34064589, 2021). "On the other hand, breast cancer cell-derived versican promoted a M2 phenotype." (PMID 33466303, 2021). "Interestingly, dos Reis and co-workers recently demonstrated the correlation of versican expression with tumor associated macrophage (TAM) accumulation and progression using two in vivo models of mammary carcinomas." (PMID 33163489, 2020). "However, thus far, the only documented substrates for ADAMTS-15 are VCAN and aggrecan, while in breast cancer, where the effects of ADAMTS-15 on cell migration were shown to involve syndecan-4, this was independent of its metalloproteinase activity." (PMID 32354091, 2020). "Indeed, hyaluronan helps creating a pro-tumor microenvironment, while versican promotes breast cancer cell self-renewal and migration." (PMID 32984031, 2020). "VCAN is reported to be essential for migration and metastasis of breast cancer and could be a potential prognostic biomarker for colon cancer." (PMID 32582282, 2020). "In fact, overexpression of versican has been showed to increase growth, proliferation and metastatic potential of a breast cancer murine model, while the versican silencing exerted an inhibitory effect on the proliferative and migratory ability of melanoma cells." (PMID 31334111, 2019). "The relationship between versican and TAMs in breast cancer development is still poorly understood." (PMID 31334111, 2019). "However, in the context of breast cancer, the most common cancer in women worldwide and cancer-related deaths in women, the role of versican remains unexplored." (PMID 31334111, 2019). "Here, we investigated the potential role of versican, a matrix proteoglycan, and its correlation with TAMs infiltrates in different stages of two different breast cancer models: spontaneous canine mammary gland carcinomas and the murine 4T1 breast cancer model." (PMID 31334111, 2019). "Moreover, versican G3 expressing breast cancer cells had a poorer response to chemotherapeutic drugs treatments, including doxorubicin or epirubicin." (PMID 29559954, 2018). "Interestingly, this example of tumor-stroma interaction is more likely to happen for CRC than for breast cancer due to differences in versican expression by neoplastic cells from colon or breast origin." (PMID 28481899, 2017). "Clinically, increased versican expression correlates to a decreased progression-free survival in prostate cancer, increased relapse in breast cancer, advanced disease and lymph node metastasis in adenocarcinomas of the lung, and is also diagnostically relevant in other cancers [reviewed in Ref." (PMID 26539408, 2015). "Indeed, the high expression of versican has been described in the interstitium at the invasive margins of breast carcinoma." (PMID 25140302, 2014). "The expression of versican in breast carcinomas has been correlated to invasiveness." (PMID 25140302, 2014). "Importantly, extracellular versican has been found to be elevated in a variety of human tumors including breast carcinoma." (PMID 25140302, 2014). "The distribution of versican in tissue samples is mostly allocated to breast cancer margins." (PMID 25140302, 2014). "Moreover, versican G3 domain enhanced breast cancer cell growth, migration, and metastasis by upregulating the EGFR mediated signaling pathways that contribute to a more metastatic phenotype." (PMID 25140302, 2014). "Thus expression of versican G3 domain both increases breast cancer cell proliferation in vitro and in vivo and also enhances tumor cell migration in vitro and systemic metastasis in vivo." (PMID 25140302, 2014).
breast carcinoma (continued). "Thus, versican stimulated MET of metastatic breast cancer cells by attenuating phospho-Smad2 levels, which resulted in elevated cell proliferation and accelerated metastases." (PMID 25140302, 2014). "In order to investigate the potential mechanisms through which versican expression promoted breast cancer cell bone metastasis, we exogeneously expressed a versican G3 domain in mouse breast cancer cell line 66c14 and mouse pre-osteoblast-like cell line MC3T3-E1." (PMID 22862967, 2012). "However, mechanistic studies evaluating versican G3 enhanced breast cancer bone metastasis are limited." (PMID 22862967, 2012). "The versican G3 domain is important in breast cancer cell growth, migration and bone metastasis." (PMID 22862967, 2012). "Versican enhances breast cancer bone metastasis not only through enhancing tumor cell mobility, invasion, and survival in bone tissues, but also by inhibiting pre-osteoblast cell growth, differentiation, which supply favorable microenvironments for tumor metastasis." (PMID 22862967, 2012). "A possible scenario for the involvement of both proteoglycans in breast cancer progression may involve the accumulation of both versican and decorin by stromal fibroblasts in response to estrogens, growth factors and cytokines." (PMID 21791066, 2011). "Individuals with overexpression of versican in breast cancer may more likely benefit from anti-EGFR therapy given known effects of EGF-like motifs in versican, a scientific consideration that warrants further evaluation." (PMID 22096483, 2011). "In the present study, we have evaluated the expression of versican and decorin in non-palpable breast carcinomas and their association with high risk mammographic findings and tumor characteristics." (PMID 21791066, 2011). "Inhibitors were used to test whether versican G3 activated breast cancer cell proliferation through EGFR-mediated signaling." (PMID 21079779, 2010). "Both selective EGFR inhibitor AG 1478 and selective MEK inhibitor PD 98059 could block this signaling pathway and prevent versican G3 induced effects on mammary cancer cell proliferation." (PMID 21079779, 2010). "We hypothesize that the G3 domain of versican influences not only the local tumor invasiveness in breast cancer but also systemic invasiveness of metastatic breast carcinoma to bone and soft tissues." (PMID 17662123, 2007). "In breast cancer, there does appears to be a greater degree of versican localization in interstitial stromal tissue within tumor cell nests versus that observed in either the tumor cells themselves or in stromal tissue of adjacent non-malignant areas of breast tissue." (PMID 17662123, 2007). "Interestingly, VCAN can control tumor metastasis and may identify previously undetected therapeutic targets to treat metastatic diseases in patients with breast cancer." (PMID 34093807, 2021). "Finally, future studies using cytokines- and versican-knockdown mice and macrophage-depleted mice could better explore the relationship between TAMs and versican in the metastatic development of 4T1 breast cancer mice model." (PMID 31334111, 2019). "Thus, we suggest that versican and TAMs as attractive targets for breast cancer therapy." (PMID 31334111, 2019). "Also, versican enhances breast cancer cell metastasis in mouse breast cancer cell lines, not only through facilitating cell motility and invasion but also by inhibiting preosteoblast cell growth and differentiation which supply favourable microenvironments for tumor metastases." (PMID 25140302, 2014). "Versican G3 domain appears to be important in local and systemic invasiveness of human breast cancer; our previous investigation demonstrated that versican G3 domain enhanced breast cancer cell growth, migration and systemic metastasis by up-regulating the EGFR-mediated signaling pathway." (PMID 22096483, 2011).